ERAP1 (endoplasmic reticulum aminopeptidase 1)
Diseases named in the same sentence as ERAP1 in open-access papers (continued):
Sharing a sentence is not in itself a finding about the gene and the disease.
cancer (continued). "In addition to SNPs and mutations, loss of heterozygosity has been shown to be an important genetic factor in human carcinomas; in the present study, complete and partial LOH and haplotype loss were found to occur in a considerable proportion of cases with ERAP1 downregulation (up to 50%)." (PMID 26146606, 2015). "Thus, this was the first demonstration that tampering with ERAP1 activity via reduction of its expression can result in increased tumor immunogenicity in vivo, and may represent a novel pathway for anti-cancer therapeutic exploitation." (PMID 22942706, 2012). "Overall, ERAP1 and ERAP2 play crucial roles in cancer, affecting peptide processing and presentation on HLA molecules, thereby influencing the immune response to malignant cells." (PMID 38534723, 2024). "ERAP1 and ERAP2 are potential anti-cancer targets activating immune responses against malignant cancers by promoting T and NK cell-mediated cytotoxic responses." (PMID 36834865, 2023). "Studies in the transcriptional and post-transcriptional regulation of ERAP1 and ERAP2 have also been investigated in a cancer immunity setting." (PMID 36834865, 2023). "Accordingly, inhibition of ERAP1 was shown to generate strong innate and adaptive anti-tumor immune responses resulting in tumor regression in two distinct tumor mouse models, thus providing evidences that modulation of ERAP1 activity may represent a promising tool for cancer immunotherapy." (PMID 31341163, 2019). "It was reported that MHC-I antigen presentation is downregulated in cancer cells of epithelial origin by abnormalities in the antigen processing machinery, which include MHC-I heavy chains, β2M, immunoproteasome subunits, TAP, Tapasin, and ERAP1." (PMID 39116074, 2024). "In addition to their involvement in the immune system, ERAP1, and ERAP2 also play a role in cell migration and angiogenesis, which are necessary for both pregnancy and cancer." (PMID 36834865, 2023). "Overall, research into the effects of ERAP1 and ERAP2 on pregnancy and cancer could yield a new understanding of the conditions and potential treatments for pregnancy complications and cancer, which affect many lives every day." (PMID 36834865, 2023). "In particular, the impacts of ERAP1 and ERAP2 on pregnancy and cancer should be explored further." (PMID 36834865, 2023). "The critical role of the ERAP1 and ERAP2 aminopeptidases in antigen processing presents a unique target to affect T cells responses with relevance to infection, autoimmunity, and immunosurveillance of cancer." (PMID 36569828, 2022). "Furthermore, endoplasmic reticulum aminopeptidases, ERAP1 and ERAP2, exhibit variable expression levels in different cancer types." (PMID 33406696, 2021). "ERAP1 and ERAP2 may be important targets that enhance T and NK cell-mediated immune responses against established cancers." (PMID 32596278, 2020). "Taken together, our analyses suggest that the effects on the proteome of cancer cells induced by ERAP1 inhibition or ERAP1 KO are not limited to the A375 cell line but may extend to other cancer cell types as well." (PMID 40189142, 2025). "Hence, various ERAP1 inhibitors have been developed to modulate antigen presentation, including GRWD5769, which is currently undergoing Phase I/II clinical trials in patients with advanced cancers." (PMID 40265075, 2025). "Analysis of ERAP1 and ERAP2 expression by malignant cells has shown that the levels of these enzymes undergo significant changes that may correlate with the ability of cancer cells to evade immune responses." (PMID 38534723, 2024). "This fact may indicate that the complete absence of ERAP1 in the ER might also not be beneficial for cancer development." (PMID 37101107, 2023). "The results presented here may suggest the important role for ERAP1 in the anti-cancer response, which is different in smokers versus never-smokers, depending to some extent on the presence of ERAP2, and affecting NSCLC clinical course." (PMID 34149699, 2021).
cancer (continued). "Although our observations may not extend to noncancer cell lines, ERAP1 is a pharmacological target in cancer therapy and any effects of its inhibition on cancer cell function may have to be validated and evaluated separately to its effect on the immune responses." (PMID 40189142, 2025). "When the expression of MHC I pathway genes was analyzed by qPCR, we found reductions in transcripts of TAP1, TAP2, and ERAP1 genes (other MHC I pathway genes were not examined), which was consistent with our earlier studies with other cancers." (PMID 39354629, 2024). "In addition to the possible role of the activity of ERAP1 and ERAP2 on the normal immune control of cancer, a series of recent studies have highlighted that these two enzymes may be important pharmacological targets for boosting immune responses to established cancers." (PMID 25566501, 2014). "On the other hand, highly active ERAP1 without the presence of functional ERAP2, may appear to be suitable to produce cancer epitopes effectively recognized by immune cells capable of eliminating cancer cells." (PMID 34149699, 2021).
tumor (47 papers, 2012 to 2025). "Downregulation of ERAP1 activity causes reduced presentation of pathogenic antigens, and inability to effectively induce cellular immune rejection in patients, allowing tumour cells to continue to grow." (PMID 39823241, 2025). "At 46 days post injection all control mice were dead, whereas 60% of sgE-1 tumor-bearing mice were alive, suggesting that loss of ERAP1 renders 9464D tumors responsive to entinostat treatment." (PMID 39438988, 2024). "As loss of ERAP1 has been associated with reduced cell proliferation in some tumor models, we evaluated the proliferation rate of ERAP1 KO and control cells under 2D and 3D growth conditions as well as cell cycle, apoptosis and cell migration." (PMID 39438988, 2024). "Overall, these data suggest that loss of ERAP1 expression makes tumor cells more susceptible to killing by immune cells, as a result of increased release of inflammatory cytokines and recruitment and activation of immune effector cells." (PMID 39438988, 2024). "In esophageal carcinoma lesions, the expression of ERAP1 was lost or down-regulated in 20 and 28% of cases, respectively, and significantly associated with the depth of tumor invasion." (PMID 37101107, 2023). "We showed that carriers of the rs26653C allele (GC + CC) had an almost twofold higher level of ERAP1 compared to patients with the GG genotype, but the difference was seen only in non-tumor control tissue." (PMID 37101107, 2023). "A similar enhanced response of anti-PD-L1 was also seen in an ERAP1-deficient mouse transplantable tumor model." (PMID 36834865, 2023). "An immune-evading tumor can be using ERAP1/ERAP2 to destroy tumor-associated antigenic peptides and over-expresses immune checkpoints such as PD-L1 to avoid T cell responses." (PMID 33406696, 2021). "Loss of ERAP1 function results in the generation of a new immunopeptidome, which stimulates anti-tumor immune responses determining the tumor regression of different mouse models." (PMID 31341163, 2019). "In these tissues, ERAP1 expression was lost or down-regulated in 20 and 28% of cases, respectively, and significantly associated with the depth of tumor invasion." (PMID 25566501, 2014). "In another study, down-regulation of ERAP1 elicited specific CTL responses against a cryptic tumor-associated antigen that was normally destroyed by ERAP1, resulting in tumor growth arrest and enhanced survival." (PMID 25566501, 2014). "We next evaluated the effect of ERAP1 deficiency on tumor growth in vivo." (PMID 39438988, 2024). "We also attempted to determine whether ERAP1 mRNA levels measured in the tumor are associated with some clinical parameters." (PMID 37101107, 2023). "ERAP1 is over-expressed in a number of tumor cell lines, and ERAP1-deficient tumor cells are more susceptible to NK cell mediated lysis, the latter possibly due to altered interactions of MHC class I molecules with the NK cell inhibitory receptors (e.g. Ly49C)." (PMID 23894499, 2013). "It has also been proposed that ERAP1 has an important role in modulating tumor susceptibility." (PMID 23894499, 2013). "The immune response escape of tumor cells by the imbalance of ERAP2/ERAP1 was further supported by prior studies, in which a decreased HLA class 1 surface expression was observed together with this imbalance, thereby reducing the tumor-associated peptide antigen presentation." (PMID 37372322, 2023). "Greywolf Therapeutics demonstrated their first-in-class ERAP1 inhibitors in combination with anti-PD1 inhibited tumor growth in syngeneic mice tumor models." (PMID 40141198, 2025). "ERAP1 activity was detectable by two-photon imaging on tumour sections at an imaging depth of 50–120 μm." (PMID 40265075, 2025). "Inhibition of ERAP1 results in the generation of new antigens able of inducing potent anti-tumor immune responses." (PMID 39438988, 2024).
tumor (continued). "We and others have previously shown that the immunopeptidome change generated by ERAP1 silencing is able to influence the anti-tumor responses mediated by T cells and NK cells." (PMID 39438988, 2024). "Cocultures of splenocytes derived from 9464D bearing mice and tumor cells allowed the assessment of the effect of ERAP1 inhibition on the secretion of inflammatory cytokines and activation and migration of immune cells towards ERAP1 KO cells by FC." (PMID 39438988, 2024). "Inhibition of ERAP1 in combination with PD-1 blockade results in increased tumor-specific immune response and T-cell receptor (TCR) repertoire diversity in several syngeneic tumor models." (PMID 39438988, 2024). "Western blot analysis revealed a higher expression of ERAP1 in the 9464D cell line, prompting us to select this tumor model for further experiments." (PMID 39438988, 2024). "Many SNPs in ERAP1 and ERAP2 are associated with pregnancy complications such as pre-eclampsia or tumor risks." (PMID 36834865, 2023). "Inhibition of ERAP1 controls Hh-induced tumor growth, suggesting that ERAP1 is a promising therapeutic target in Hh over-activated tumors." (PMID 37853413, 2023). "The involvement of ERAP1 in the generation and destruction of tumor antigens has been endorsed by many other studies." (PMID 35936007, 2022). "Our previous studies revealed that ERAP1 controls the interaction of inhibitory KIRs with their specific ligands in some tumor cells and lymphoblastoid cell lines." (PMID 34917091, 2021). "Recently, functional ERAP1 allotypes have been correlated with tumor-infiltration by CD8+ T cells in cervical and oropharyngeal squamous cell carcinomas due to changes in processing of particular antigenic epitopes." (PMID 33406696, 2021). "Inhibition of ERAP1 or ERAP2, can help reactivate such responses by protecting tumor-associated antigenic peptides from degradation." (PMID 33406696, 2021). "Compared to controls, mice engrafted with GCPs overexpressing ERAP1 showed an increased tumor growth rate, tumor volume (at the end point), and expression of Gli1 and CyclinD2, accordingly with the role of ERAP1 in promoting Hh signaling." (PMID 31341163, 2019). "As expected, inhibition of ERAP1 significantly reduced tumor growth compared to controls, resulting in a decrease in endogenous Hh target genes at both mRNA and protein levels." (PMID 31341163, 2019). "Together, these data identify a molecular mechanism in the regulation of Hh signaling and unveil the relevance of ERAP1 in the control of Hh-dependent tumor growth." (PMID 31341163, 2019). "Remarkably, both genetic and pharmacological inhibition of ERAP1 suppresses Hh-dependent tumor growth in vitro and in vivo, suggesting an innovative therapeutic approach in the treatment of Hh-dependent tumors." (PMID 31341163, 2019). "It is noteworthy that tumor necrosis binding pathway was dysregulated with differentially expressed genes Tnfsf13, Erap1, Tnfsf10, and Nucb2 (p < 0.05)." (PMID 31888290, 2019). "Remarkably, genetic or pharmacological inhibition of ERAP1 suppresses Hh-dependent tumor growth in vitro and in vivo." (PMID 31341163, 2019). "The relevance of ERAP1 on Hh-dependent tumor cell growth was determined by testing short-term cultures of primary MB cells freshly isolated from Math1-cre/PtcC/C mice tumors, one the most used model to study the Hh-dependent tumorigenesis." (PMID 31341163, 2019). "Subsequently, we performed an evaluation of possible molecular mechanisms for inactivation of the ERAP1 gene in flow sorted tumor cells from this series of clinical specimens." (PMID 26146606, 2015). "In one study, the authors showed that ERAP1 down-regulation was sufficient to stimulate the cytotoxic activity of NK cells and to result in tumor growth arrest." (PMID 25566501, 2014). "We demonstrated that interfering with ERAP1 expression ultimately leads to tumor rejection in syngeneic animals by boosting NK cell-, and subsequently T cell-mediated cytolysis." (PMID 22942706, 2012).
tumor (continued). "In tumor cells, inhibition of ERAP1 expression has been shown to modify tumor immunogenicity by shifting the balance of activating and inhibitory signals towards NK cell activation resulting in target cell killing." (PMID 22942706, 2012). "ERAP1’s established links to endothelial migration and angiogenesis reveal its potential involvement in processes such as wound healing, vascular integrity, and tumor growth through interactions with VEGF signaling, cytoskeletal dynamics, and cell adhesion." (PMID 40226591, 2025). "We hypothesize that ERAP1 inhibition, by expanding the repertoire of neoantigens presented on the surface of tumor cells, may function as a surrogate for the low TMB." (PMID 39438988, 2024). "Similarly, in human tumor cells, ERAP1 inhibition leads to NK-cell activation by altering the interaction of peptide-MHC class I complexes with NK-cell inhibitory receptors." (PMID 39438988, 2024). "Several studies have shown that inhibition of ERAP1 causes a profound change in the immunopeptidome able of inducing substantial anti-tumor immune responses by CD8+ T cells and natural killer (NK) cells resulting in the control of tumor growth." (PMID 39438988, 2024). "Inhibition of ERAP1 is presumed to potentially affect tumor immunopeptidome by a similar mechanism." (PMID 39438988, 2024). "We also investigated the possible impact of several ERAP1 variants on mRNA expression levels in tumor and non-tumor tissue." (PMID 37101107, 2023). "Down-regulation of ERAP1 mRNA observed in NSCLC tissue may be related to tumor immune evasion strategy." (PMID 37101107, 2023). "ERAP1 down-regulation may lead to less efficient processing and presentation of tumor antigens, thereby creating a less immunogenic phenotype and facilitating tumor growth and progression." (PMID 37101107, 2023). "Thus, the tumor cells of HLA class I positive HL cases show normal ERAP1 and ERAP2 expression patterns." (PMID 33499248, 2021). "Thus, they analyzed ERAP1 mRNA expression in tumor cells where the level of ERAP1 protein was known to be downregulated, comparing them to cells from patients with normal ERAP1 levels." (PMID 32183384, 2020). "Moreover, to verify the effect of ERAP1 inhibition in a natural tumor niche for MB growth, symptomatic Gfap-cre/Ptcfl/fl mice were treated with Leu-SH or vehicle for two consecutive days." (PMID 31341163, 2019). "Similarly to murine tumor models, either pharmacological or genetic inhibition of ERAP1 impairs in vitro proliferation of the human Hh-dependent MB cell line Daoy, leading to a decreased Hh-pathway activity." (PMID 31341163, 2019). "Based on the in vitro studies, we hypothesized that inhibition of ERAP1 activity may reduce tumor growth in vivo." (PMID 31341163, 2019). "Reduced cellularity associated with a decreased Ki67 and increased NeuN and cleaved Caspase-3 positive tumor cells was detected in Leu-SH treated tumor masses, indicating that ERAP1 inhibition impairs tumor growth by promoting cell differentiation and committing tumor cells to apoptosis." (PMID 31341163, 2019). "Similarly to cerebellar progenitors, the pharmacological inhibition of ERAP1 impaired both tumor cell proliferation in a dose- and time-dependent manner and clonogenic self-renewal ability." (PMID 31341163, 2019). "Overall, these data confirm the role of ERAP1 in the regulation of Hh-dependent tumor growth." (PMID 31341163, 2019). "Conversely, inhibition of ERAP1 function stabilizes βTrCP, which in turn induces ubiquitylation of Gli factors leading to proteolysis of Gli1 and Gli2 and generation of Gli3R, thereby suppressing tumor cell growth." (PMID 31341163, 2019).